RETN (resistin)
Diseases named in the same sentence as RETN in open-access papers (continued):
Sharing a sentence is not in itself a finding about the gene and the disease.
Hypertension (continued). "The discrepancy data among studies estimating the association of resistin concentration with the hypertension phenotype may derive from not taking into account particular genetic variants of resistin directly related to resistin expression level." (PMID 35565757, 2022). "Additionally, the levels of resistin in plasma may have a predictive value since it has been reported that in a young healthy population with a family history for essential hypertension, the levels of resistin in plasma were increased." (PMID 33679451, 2021). "Last but not least, the studies used in this analysis were all case-control studies, which may prove an association but do not demonstrate causation between the resistin and high blood pressure." (PMID 28525369, 2017). "Nevertheless, the transcriptome profiling might be clinically relevant if consideration were given to placing her on statins to treat her high blood pressure, given evidence that serum resistin opposes statin-mediated reduction of cholesterol production in the liver in overweight people." (PMID 26391122, 2015). "Consistent with other studies, it was significantly correlated with BMI, hypertension, and systemic inflammatory parameters: CRP, resistin, and PAI-1." (PMID 36920931, 2023). "However, in our multivariable logistic regression model SI value was an independent risk factor for hypertension and is not related to the presence of the resistin G allele that might explain obtained results." (PMID 35565757, 2022). "Although our study was conducted on healthy rats, high plasma levels of resistin have a direct relationship with cardiovascular diseases such as CHF and hypertension." (PMID 32440321, 2020). "The AUCs for resistin were higher in patients who presented asystole or PEA rhythm of CA (especially), cardiovascular comorbidities, history of congestive heart failure, arterial hypertension or post-CA shock." (PMID 31881807, 2019). "The purpose of the present study was to evaluate the association between four insulin resistance genes (ADIPOQ, LEPR, RETN, and TRIB3) and both T2DM and hypertension." (PMID 24414038, 2014). "Serum levels of adipokines, including adiponectin, leptin, and resistin, have been reported to be involved in the development and progression of both T2DM and hypertension." (PMID 24414038, 2014). "Although the cellular and molecular mechanisms through which resistin induces hypertension in diabetic individuals are not fully understood, some experimental studies in animal models have provided valuable insights." (PMID 40283140, 2025). "Statistically significant increase in the levels of resistin, CRP and TLC was seen in patients of hypertension (group B), stable angina pectoris with hypertension (group C) and myocardial infarction with hypertension (group D) as compared to normal subjects of group A (p < 0.001 for all)." (PMID 31258568, 2019). "In the present study, we showed that resistin induces hypertension and IR in wild type (WT) mice, but not in tlr4−/− mice." (PMID 26917360, 2016). "Neither hypertension (per se) nor any cardiovascular disease affected the OC-resistin relationship." (PMID 22518129, 2012). "However, whether resistin and TLR4 play a role in hypertension is largely unknown." (PMID 26917360, 2016). "Circulating resistin has also been correlated with eGFR and UAE in patients with T2DM or in individuals with hypertension but without DM." (PMID 41441015, 2025). "Statistically significant positive correlation was observed between serum resistin and TLC only in group D i.e. patients of myocardial infarction with hypertension (r=0.459, n=20, p=0.042) while correlation was non-significant between serum resistin and CRP in all four study groups (Table-III)." (PMID 31258568, 2019).
Sepsis (71 papers, 2009 to 2026). Sepsis is defined as life-threatening organ dysfunction caused by a dysregulated host response to infection. "This is manifested by an increase in serum resistin expression concentration in sepsis patients, which can also serve as a diagnostic indicator for sepsis." (PMID 40568710, 2025). "Subgroup analysis for assessing the diagnostic accuracy of resistin levels in predicting sepsis in infants and children." (PMID 40416430, 2025). "This study aims to assess the clinical potential of S100A8/A9 and resistin as novel biomarkers for predicting mortality risk in sepsis patients." (PMID 40568710, 2025). "The current study revealed that the AUC for the SROC curve of RETN was 0.93, indicating that the RETN level is a valuable diagnostic marker for sepsis in neonates and children." (PMID 40416430, 2025). "This study aimed to assess serum resistin's diagnostic potential and prognostic value in neonatal sepsis, a topic previously unexplored." (PMID 38562275, 2024). "This study with 151 neonates diagnosed with sepsis found a significant association (p < 0.05) between elevated serum resistin levels and increased mortality risk." (PMID 38562275, 2024). "Serum resistin, identified as a robust biomarker, demonstrated a clear association with adverse outcomes in neonatal sepsis, offering enhanced predictive capabilities." (PMID 38562275, 2024). "The research underlined the extended increase in serum resistin levels compared to other cytokines, underscoring its function as an acute-phase protein in sepsis and septic shock." (PMID 38562275, 2024). "Serum resistin, an adipokine linked to inflammation, has lately gained interest for its ability to predict death in newborn sepsis." (PMID 38562275, 2024). "The eQTL data supported the association between RETN RNA levels and a lower risk of sepsis-related death, while the cis-eQTL data supported this association as well as the association between RETN RNA levels and a lower risk of sepsis severity." (PMID 37834432, 2023). "This study aimed to estimate the association between resistin and sepsis by integrating multiple QTLs (expression QTLs, protein QTLs, and metabolite QTLs) with GWAS summary data." (PMID 37834432, 2023). "We conducted colocalization analyses, which showed that these CpG sites are colocalized with the risk of sepsis-related death via a shared SNP-rs3745367, located within the second intron of RETN." (PMID 37834432, 2023). "The identification of two CpG sites associated with sepsis death and RETN protein levels provides additional insight into the mechanisms underlying the protective effect of resistin in sepsis." (PMID 37834432, 2023). "Sustained elevation of both Visfatin and Resistin was associated with the severity of critical illness in patients with sepsis (APACHE II)." (PMID 36509969, 2023). "Our analysis identified two CpG sites, cg06633066 and cg22322184, that were found to be associated with both RETN protein levels and sepsis-related mortality." (PMID 37834432, 2023). "Our analysis revealed that RETN levels were negatively associated with sepsis-related 28-day mortality in the ICU." (PMID 37834432, 2023). "MR analyses were then conducted to investigate the causal relationships between resistin (one of the identified DEGs) levels and the survival of sepsis patients." (PMID 37834432, 2023). "The pQTL data supported the association between resistin protein levels and a lower risk of sepsis-related death and severity, while the cis-pQTL data supported these associations as well." (PMID 37834432, 2023). "RETN also mediates immunosuppression, directly suppresses neutrophil function, and is associated with poor outcomes in sepsis." (PMID 36855207, 2023). "Based on MR analyses of multi-omics QTL and GWAS data, we provide evidence for a causal effect of resistin on sepsis death, which is a crucial step towards the development of effective treatments for this life-threatening condition." (PMID 37834432, 2023).
Sepsis (continued). "By utilizing MR analyses based on the joint analysis of eQTLs, pQTLs, meQTLs, and GWASs data, a valid test for the presence of a causal relationship between resistin and sepsis can be provided." (PMID 37834432, 2023). "Elevated RESISTIN signaling has been associated with adverse outcome in sepsis in the Albumin Italian Outcome Sepsis (ALBIOS) trial." (PMID 35634310, 2022). "For example, RETN encodes resistin, which is strikingly elevated in patients with sepsis and is associated with sepsis severity and outcomes." (PMID 33132754, 2020). "Our group and others have shown that resistin (RETN), a recently discovered inflammatory cytokine, is significantly upregulated in septic shock and sepsis-associated acute kidney injury (AKI)." (PMID 31147868, 2019). "Circulating myeloid cells produce the cytokine resistin (RETN), which has been associated with poor outcomes in sepsis/septic shock and can directly inhibit neutrophil function." (PMID 31147868, 2019). "Distribution of area under the curve of resistin level, cut-off point, and diagnostic accuracy of sepsis by control groups, age and time." (PMID 31555623, 2019). "The present study demonstrated that resistin levels on the first, fourth, and seventh day were statistically associated with sepsis." (PMID 31555623, 2019). "The diagnostic accuracy of resistin level was high for discriminating sepsis (area under the receiver operating characteristic curve [AUC] 0.864 [SE = 0.41])." (PMID 31555623, 2019). "Accordingly, resistin is associated with an array of inflammatory diseases including sepsis, inflammatory bowel disease, arthritis and astma." (PMID 30517161, 2018). "Here we explore neutrophil responses, in particular the release of sepsis-associated factors heparin-binding protein (HBP) and resistin in relation to specific bacterial stimuli and sepsis of varying aetiology." (PMID 26887258, 2016). "First we measured HBP and resistin levels in acute phase plasma of patients with severe sepsis/septic shock caused by different bacteria." (PMID 26887258, 2016). "These include BATF3, which encodes a leucine zipper protein that functions as a transcriptional repressor, and RETN, which encodes resistin, a serum adipokine that is elevated by sepsis." (PMID 22174891, 2011). "High resistin levels (> 10 ng/ml) were associated with an unfavourable outcome in non-sepsis patients on ICU and the overall survival." (PMID 19545363, 2009). "Several studies have shown that the RETN level may be a specific marker for the early identification of patients at increased risk of sepsis." (PMID 40416430, 2025). "Additionally, we measured the serum levels of S100A8/A9 and resistin only on the first day of admission and assessed their association with short-term sepsis mortality risk." (PMID 40568710, 2025). "Consistent with our results, resistin has been found in elevated concentrations in the blood of patients and may be linked to an inflammatory cytokine network in the acute phase of sepsis." (PMID 38672079, 2024). "Further studies have linked resistin to the severity of sepsis using clinical scoring outcomes." (PMID 38672079, 2024). "Additionally, we identified two CpG sites, cg06633066 and cg22322184, that were associated with RETN protein levels and sepsis death, providing novel insights into the underlying mechanisms of sepsis." (PMID 37834432, 2023). "Indeed, an association of resistin levels with the SOFA score in patients with sepsis was also shown by others." (PMID 37238973, 2023). "Of particular importance is that we discovered an SNP (rs3745367) that plays a causal role in both RETN protein expression and sepsis pathogenesis through the Mendelian randomization of cis-meQTL, along with a closely related CpG site (cg02346997, cg06633066, and cg22322184)." (PMID 37834432, 2023). "Interestingly, we identified GYG1 and RETN as diagnostic markers for sepsis in VLBW infants through WGCNA analysis and machine learning algorithms." (PMID 37139640, 2023).
Sepsis (continued). "Nevertheless, the associations between resistin and sepsis remain to be fully understood." (PMID 37834432, 2023). "Notably, we provided the first demonstration of a specific causal and protective role of resistin in sepsis-related mortality among ICU patients." (PMID 37834432, 2023). "Interestingly, resistin production was associated with higher Ly6Chi monocyte counts both at 6 h following sham surgery (P = 0.026) and at 6 h following sepsis (P = 0.0062)." (PMID 35286340, 2022). "Similarly, there is evidence on the association between increasing resistin concentration and mortality in critically ill patients with sepsis and traumatic brain injury, for instance." (PMID 33651847, 2021). "In this study we explore whether neutrophil responses, in particular the release of the sepsis-associated factors HBP and resistin, differ depending on stimuli and how this relates to sepsis of varying aetiology." (PMID 26887258, 2016). "Therefore, we further investigated the causal relationship between RETN levels and sepsis." (PMID 37834432, 2023). "Furthermore, we investigated the underlying CpG sites located within RETN or its promoter, which may affect sepsis outcomes." (PMID 37834432, 2023). "In accordance with these reports, significantly higher resistin levels were found in septic patients, and resistin levels were associated with severity of sepsis supporting the hypothesis that resistin predominantly participates in systemic inflammatory response to infection." (PMID 22272381, 2012). "Resistin is a cytokine that promotes an inflammatory response, and its expression is significantly increased in sepsis and septic shock." (PMID 41602873, 2026). "The proinflammatory adipokine RETN has subsequently been found to be elevated during sepsis in an intensive care unit (ICU)." (PMID 40416430, 2025). "Among the six articles that met our inclusion criteria, we examined the correlation between RETN levels and neonatal and paediatric sepsis." (PMID 40416430, 2025). "In conclusion, on the basis of the currently available evidence, RETN levels are highly valuable for early detection of neonatal and paediatric sepsis." (PMID 40416430, 2025). "Further prospective controlled studies with adequate sample sizes that encompass all predisposing factors for sepsis are necessary to elucidate the relationship between RETN levels and sepsis." (PMID 40416430, 2025). "This analysis underscores the importance of multiple immunomodulatory proteins, particularly CD27, KLRB1, RETN, and CD163, in the risk of clinically overt sepsis, suggesting their potential as candidates for disease prognosis and treatment targets." (PMID 41472734, 2025). "Survival analysis revealed significant associations of KLRB1, RETN, and CD163 with sepsis prognosis." (PMID 41472734, 2025). "In this study, three core genes (CD163, MCEMP1 and RETN) that lead to sepsis death in children were screened out, providing a new understanding of the lethal mechanism of sepsis in children and a promising new therapeutic approach." (PMID 40599778, 2025). "In patients with a normal sepsis phenotype, those with high serum resistin levels (≥ 63.695 ng/mL) had a lower survival rate compared to those with low resistin levels (< 63.695 ng/mL)." (PMID 40568710, 2025). "For instance, on the day of admission, resistin levels in patients with G- sepsis were considerably elevated than in those with G+ sepsis." (PMID 40568710, 2025). "For sepsis patients with a normal phenotype, the resistin cut-off for predicting 28-day mortality was 63.695 ng/ml." (PMID 40568710, 2025). "In our cohort, high RETN expression correlated with poorer prognosis in sepsis patients, although its apparently stage-dependent, dual actions warrant further investigation." (PMID 41472734, 2025). "Elevated levels of proinflammatory adipokine RETN have been observed during ICU sepsis and have been studied as a potential indicator of neonatal sepsis." (PMID 40599778, 2025).
Sepsis (continued). "In contrast, S100A8/A9 and resistin as sepsis biomarkers not only aids in diagnosing sepsis but also distinguishes between severe sepsis, G- and G+ infections, and different immune subtypes of sepsis patients." (PMID 40568710, 2025). "The aim of this study was to investigate the utility of serum resistin levels as a prognostic indicator for mortality in neonates diagnosed with sepsis." (PMID 38562275, 2024). "Our study results confirm and refine other studies’ reports about resistin serum levels in critically ill patients (including those with severe burns, sepsis, trauma)." (PMID 39062875, 2024). "Consistent with the bioinformatics predictions, our ELISA results substantiate a significant elevation in Resistin expression among individuals affected by sepsis." (PMID 38951753, 2024). "In particular, adiponectin, leptin, resistin, visfatin, chemerin, and omentin increase at sepsis onset, and their kinetics in the early phase of sepsis are associated with sepsis mortality." (PMID 38540711, 2024). "These analyses were employed to identify the optimal resistin cut-off for distinguishing patients with sepsis." (PMID 38562275, 2024). "Linked to inflammatory responses in various disorders, interest in using resistin as a sepsis biomarker has surged, with limited research focusing on neonates." (PMID 38562275, 2024). "Of these, six hub genes (CD247, CD2, CD40LG, KLRB1, LCN2, RETN) showed significant alterations across COVID-19, sepsis, and geriatric sepsis-induced ARDS." (PMID 37822934, 2023). "The results showed that the expression levels of RETN and THBS1 were lower in the survival group, which indicated that high expression of RETN and THBS1 was associated with a poor prognosis in the sepsis group." (PMID 37060578, 2023). "In this research, we have disclosed, through robust and causal evidence obtained from MR analyses, the protective role of resistin in sepsis, particularly in critically ill patients." (PMID 37834432, 2023). "A significant increase in the expression of GYG1 and RETN was observed in VLBW infants with sepsis in both the training and testing datasets." (PMID 37139640, 2023). "The results showed that the expression levels of RETN and THBS1 were lower in the survival group, indicating that high expression of RETN and THBS1 is associated with poor prognosis in sepsis." (PMID 37060578, 2023). "RETN was found to be upregulated in macrophages during sepsis through the analyses of single-cell transcriptome data." (PMID 37834432, 2023). "Despite these limitations, point estimates for the genetically predicted effect of resistin on sepsis death were consistent across multi-QTL data, which is encouraging." (PMID 37834432, 2023). "For instance, experimental models of human sepsis and studies of critically ill patients with sepsis or septic shock reveal elevated resistin levels." (PMID 37834432, 2023). "The expression levels of RETN were upregulated in sepsis samples compared to healthy controls in bulk transcriptome data." (PMID 37834432, 2023). "Our findings revealed significant decreases in CD4, CD3e, IL-7R, CD5, CD247, CD2, CD40LG, ITK, and KLRB1, and significant elevations in MMP9, LCN2, and RETN in sepsis-induced ARDS compared to controls." (PMID 37822934, 2023). "Through the examination of single-cell transcriptome data, RETN was found to be upregulated in macrophages during sepsis." (PMID 37834432, 2023). "Recently, proteomics and RNA sequencing screening have demonstrated that RETN is highly expressed in the plasma of sepsis patients." (PMID 37060578, 2023). "For example, in sepsis patients, RETN showed a strong positive correlation with macrophages and a significant negative correlation with Th17 cells." (PMID 37060578, 2023). "An observational study also found that resistin levels were higher in infants with severe sepsis or those who required mechanical ventilation." (PMID 37834432, 2023).